MAP2K4 (mitogen-activated protein kinase kinase 4)
Diseases named in the same sentence as MAP2K4 in open-access papers (continued):
Sharing a sentence is not in itself a finding about the gene and the disease.
osteoarthritis (4 papers, 2017 to 2026). A noninflammatory degenerative joint disease occurring chiefly in older persons, characterized by degeneration of the articular cartilage, hypertrophy of bone at the margins and changes in the synovial membrane. "miR-145 attenuates TNF-α-driven cartilage matrix degradation in osteoarthritis by suppressing mitogen-activated protein kinase kinase 4 (MKK4) expression." (PMID 29844019, 2018).
Insulin resistance (3 papers, 2017 to 2025). Increased resistance towards insulin, that is, diminished effectiveness of insulin in reducing blood glucose levels. "Map2k4 activates p38 and JNK kinases which have been implicated as drivers of HFD-induced insulin resistance, and based on the behaviour of S78, the orchestration of this detrimental signalling axis in HFD-feeding may depend on genetic background." (PMID 38329473, 2024).
myocardial infarction (3 papers, 2024 to 2025). Gross necrosis of the myocardium, as a result of interruption of the blood supply to the area, as in coronary thrombosis. "Promoting angiogenesis is achieved by inhibition of miRNA-92after both induced myocardial infarction and damage to carotid arteries in ratsthrough upregulating endothelial proteins, mitogen-activated protein kinase kinase 4(MKK4) and KLF4." (PMID 40475735, 2025).
non-small cell lung carcinoma (3 papers, 2021 to 2023). A group of at least three distinct histological types of lung cancer, including non-small cell squamous cell carcinoma, adenocarcinoma, and large cell carcinoma. "For instance, lncRNA HNF1A-AS1 binds with miR-92a-3p and enhances the radioresistance of non-small-cell lung cancer (NSCLC) by competitively regulating the MAP2K4/JNK axis." (PMID 36139006, 2022).
endometrial carcinoma (2 papers, 2019 to 2022). A malignant tumor arising from the epithelium that lines the cavity of the uterine body. "In previous study, low MAP2K4 expression and positive Vimentin expression were reported to be associated with poor prognoses in endometrial carcinoma." (PMID 31761784, 2019). "MAP2K4 was exhibited brain-specific gene and to play essential roles in the regulation of cell proliferation in AD, while MAP2K4 was related with the condition and prognosis of endometrial carcinoma." (PMID 36506318, 2022).
gastric adenocarcinoma (2 papers, 2021 to 2024). "A loss‐of‐function mutation in the CBP/CREBBP gene, which encodes a HAT, is common to many cancers, including GC, and MAP2K4 loss of expression has been reported in gastric adenocarcinoma associated with poor survival." (PMID 33724653, 2021). "Among these genes, MAP2K4 and NRAS are reported as driver genes by IntOGen, while NTRK3 is listed as a driver gene for esophageal cancer and stomach adenocarcinoma." (PMID 39554798, 2024).
liver cancer (2 papers, 2023 to 2025). An epithelial or non-epithelial malignant neoplasm that arises from the liver. "Similarly, similar to MAP2K3, low expression of MAP2K4 can predict the occurrence of liver cancer, and high expression of MAP2K4 predicts better prognosis of patients." (PMID 40587753, 2025).
nasopharyngeal carcinoma (2 papers, 2021 to 2022). A carcinoma arising from the nasopharyngeal epithelium. "It has been proposed that the elevated miR-BART22 and decreased MAP2K4 expression may be important markers to predict poor prognosis in patients with nasopharyngeal carcinoma." (PMID 36237327, 2022). "Further investigation has revealed that CB can powerfully reverse EBV-miR-BART22-induced cisplatin resistance via upregulating MAP2K4 to antagonize Myh9/GSK3β/β-catenin and its downstream tumor stemness and EMT signals in nasopharyngeal carcinoma." (PMID 36237327, 2022).
Alzheimer disease (1 paper, 2023). A progressive, neurodegenerative disease characterized by loss of function and death of nerve cells in several areas of the brain leading to loss of cognitive function such as memory and language. "The MAP2K4 gene has been previously implicated in the pathogenesis of Alzheimer's disease." (PMID 37664790, 2023).
asthma (1 paper, 2022). "The function of MAP2K4 in asthma, a respiratory disease caused by tracheal obstruction owing to aberrant growth and migration of airway smooth muscle cells (ASMCs), has been demonstrated." (PMID 36163195, 2022). "In asthma, downregulation of MAP2K4 facilitates the proliferative and invasive capabilities of ASMCs, while overexpression of MAP2K4 represses ASMC proliferation and invasion." (PMID 36163195, 2022).
Astrocytoma (1 paper, 2018). "With respect to the role of MAP2K4 as a driver of malignancy, we assessed miR-744 expression in human brain tissue, in Astrocytoma WHO grade II/III, and in the most malignant brain tumor (i.e., GBM)." (PMID 30366472, 2018).
autoimmune disease (1 paper, 2021). A disorder resulting from loss of function or tissue destruction of an organ or multiple organs, arising from humoral or cellular immune responses of the individual to their own tissue constituents. "AS of MAP2K4 has been found in rheumatoid arthritis, as well as in pathways of patients with other autoimmune diseases." (PMID 34857024, 2021).
CAEBV infection (1 paper, 2006). "Eventually, we found several genes with expression levels significantly higher in cell lines established from NK/T-cell lymphoma than those from CAEBV infection: FGF14, PDCD4, PCNA, MAP2K4, ITGAX and AKAP2 were preferentially expressed in SNK/T cells established from nasal NK/T lymphoma." (PMID 16449999, 2006).
chronic lung disease (1 paper, 2024). According to the definitions of the American and British Thoracic Societies, including pulmonary functional tests, X-rays, and CT scans for items such as fibrosis, bronchiectasis, bullae, emphysema, nodular or lymphomatous abnormalities. "In upregulated miRNAs in the serum, hsa-miR-627-5p can restrain pulmonary artery smooth muscle cell dysfunction by targeting MAP2K4 and PI3K/AKT signaling and chronic lung disease, the most common complication in preterm infants." (PMID 38304545, 2024).
colorectal adenoma (1 paper, 2015). An adenoma that arises from the colon or rectum. "Most interestingly, in the Gaspar Colon colorectal adenoma dataset Bcl6 expression was significantly positively correlated with MAPK9, MAP2K4 and Yes1, and negatively with Dlg2, relative to normal intestinal mucosa." (PMID 26187947, 2015).
dementia (1 paper, 2012). Loss of intellectual abilities interfering with an individual's social and occupational functions. "Two key proteins in the MAPK pathway, MAP2K2 (MEK2) and MAP2K4 (JNK), were also further validated by western blotting analysis using 4 samples from HAD and 4 samples from HIV non-dementia group, respectively." (PMID 23190615, 2012).
endometrioid tumor (1 paper, 2012). A benign, borderline, or malignant epithelial tumor of the female reproductive system characterized by the presence of glands and/or cysts lined by neoplastic cells that resemble endometrial cells.
gingivitis (1 paper, 2019). A disorder involving inflammation of the gums; may affect surrounding and supporting structures of the teeth. "Notably, MAP2K4 from the MAPK pathway was down-regulated (>2-fold) specifically by the commensal biofilm, and the immune stimulatory molecule IL12A was down-regulated >10-fold by the cariogenic biofilm (compared to 2-fold down-regulation by commensal biofilm and no regulation by gingivitis biofilm)." (PMID 31448244, 2019).
leiomyosarcoma (1 paper, 2023). An uncommon, aggressive malignant smooth muscle neoplasm, usually occurring in post-menopausal women. "PLX8725, a novel MAP2K4 inhibitor, demonstrates promising in vivo activity against patient-derived xenografts of uterine leiomyosarcomas harboring gain-of-function alterations in the MAP2K4 gene." (PMID 38137334, 2023).
lymph node metastasis (1 paper, 2019). "MAP2K4 and Vimentin co-expression levels were positively correlated with the pathologic grade, tumor size, lymph node metastasis presence, and invasion (P<0.001)." (PMID 31761784, 2019).
Lymphatic Metastasis (1 paper, 2025). Transfer of a neoplasm from its primary site to lymph nodes or to distant parts of the body by way of the lymphatic system. "MAP2K4 was not statistically significant in patients with lymphatic metastasis N0 and N1 (P > .05)." (PMID 40587753, 2025).
ovarian tumors (1 paper, 2011). "We screened for mutations in MAP2K4 using High Resolution Melt analysis of 149 primary ovarian tumors and methylation at the promoter using Methylation-Specific Single-Stranded Conformation Polymorphism analysis of 39 tumors." (PMID 21575258, 2011). "We have previously reported that recurrent homozygous deletions appear to specifically target MAP2K4 in primary ovarian tumors, and the gene lay in a minimal region of loss of heterozygosity (LOH) in 68% (72/106) of the cases, the second most frequent locus targeted by LOH." (PMID 21575258, 2011). "We did not detect any methylation at the MAP2K4 promoter in ovarian tumour tissue, consistent with one other study to date." (PMID 21575258, 2011).
pancreatitis (1 paper, 2024). Inflammation of the pancreas. "In a model of inflammatory ductal metaplasia, mice with the dual loss of MAP2K4 and MAP2K7 could not efficiently resolve pancreatitis, leading to only partial acinar regeneration." (PMID 39717752, 2024).
prostatic intraepithelial neoplasia (1 paper, 2024). "Increased levels of MAP2K4, MAP2K6, and MAP2K7 in mouse prostate TRAMP model and tissues from patients with high-grade prostatic intraepithelial neoplasia." (PMID 39717752, 2024).
cancer (103 papers, 2008 to 2025). A tumor composed of atypical neoplastic, often pleomorphic cells that invade other tissues. "RB1-mutated subclone was the prominent subclone and accounted approximately 65.6% of all cancer cells while the MAP2K4-mutated subclone played a minor role." (PMID 35267640, 2022). "Small to large decreases, e.g., MAP2K4 in #33, in the frequency of minor mutations in organoids were considered to be partly due to the clonal evolution of cancer cells during organoid culture." (PMID 33483567, 2021). "The high variant allele fraction of the translocation, the loss of the other copy of MAP2K4, the recurrent loss-of-function mutations found in this gene in other cancers, and the important function of MAP2K4 indicate that this translocation is potentially a driver mutation." (PMID 34158539, 2021). "The loss-of-function mutation in MAP2K4 has been observed to be highly frequent in several cancers." (PMID 32373524, 2020). "Our findings suggest that cancers having mutations in MAP3K1 or MAP2K4, which are frequent in tumors of breast, prostate and colon, may respond to MEK inhibitors." (PMID 29795445, 2018). "While mutations in MAP2K4 have been reported here and elsewhere, the role of MAP2K4 in cancer has remained complex and contradictory." (PMID 26894955, 2016). "Patients with CRC exhibited reduced activity of the protein encoded by the MAP2K4 gene compared to healthy individuals; moreover, this loss of activity correlated with the occurrence of cancer metastases to lymph nodes and distant organs and with the clinical stage of the primary cancer." (PMID 41515982, 2025). "Interestingly, MAP2K4 has been identified as a mutational cancer driver in cholangiocarcinoma." (PMID 35603298, 2022). "MAP2K mRNA expression varied with gender (P < .0001), cancer stage (P < .05), tumor grade (P < .05), and with node metastasis status (P < .05), except for MAP2K4." (PMID 40587753, 2025). "Higher levels of MAPK8 and MAP2K4 gene expression were most frequently correlated with the lowest stage of cancer (stage 1 compared to stage 4) (p = 0.0036; p = 0.0339)." (PMID 41515982, 2025). "The selective deletion of MAP2K4/MKK4 in the pancreas of mice accelerates cancer development when combined with the tissue-specific expression of mutant KrasK12D." (PMID 40723241, 2025). "Other transcription factors that were reported to inhibit PTEN expression in several cancer models were: mitogen-activated protein kinase kinase-4 (MKK4) and B-lymphoma Moloney murine leukemia virus (Mo-MLV) insertion region 1 (BMI1)." (PMID 37205308, 2023). "Another candidate for which targeted drugs with clinical approval in other cancer entities are readily available was the mitogen-activated protein kinase kinase 4 (MAP2K4)." (PMID 36906590, 2023). "In cancer, MAP2K4 has the potential to activate phosphoinositide-3-kinase (PI3K)/AKT signaling, which can result in cell proliferation, migration, and invasion." (PMID 37859946, 2023). "As cancers that have lost MAP3K1 or MAP2K4 fail to activate JNK, loss-of-function mutations in MAP3K1 or MAP2K4 confer sensitivity to MEK inhibition, as shown in cell cultures and patient-derived xenograft (PDX) models." (PMID 36358725, 2022).
cancer (continued). "So far, our results have suggested that miR-744 acts as a counterpart of its host gene MAP2K4, an enhancer of cancer progression." (PMID 30366472, 2018). "One of its members, Mitogen-Activated Protein Kinase Kinase 4 (MAP2K4), is a well-known tumorigenic kinase with an established role in metastasis, invasion, and cancer progression." (PMID 30366472, 2018). "Recently, we showed that cancers that fail to activate JNK-JUN, due to inactivating mutations in upstream kinases MAP3K1 and MAP2K4, are sensitive to MEK inhibition." (PMID 30482246, 2018). "Our data also predict that inhibitors of the MAP3K1, MAP2K4 or JNK kinases should also show synergy with MEK inhibition in a variety of cancers." (PMID 29795445, 2018). "This negative impact of miR-744 on tumor cell migration strongly contrasts with the functions of its host gene, MAP2K4, which has been shown to profoundly enhance cancer cell migration and metastasis." (PMID 30366472, 2018). "It was found that miR-27a functioned as a tumor promoter in various cancers through targeting MAP2K4, AGGF1, prohibitin, and other genes that regulate specificity protein transcription factors and the G2-M checkpoint." (PMID 25329674, 2014). "Using several different human normal and cancer prostate cell lines and transient engineered expression of MAP2K4, our group demonstrated that MAP2K4 increases cell invasion, a critical indication of metastatic progression in vitro." (PMID 25019290, 2014). "The role of MAP2K4 in human PCa cancer progression, and the development of metastasis in particular, is controversial." (PMID 25019290, 2014). "Some of the upregulated genes are related to CSC/’cancer stemness’ such as CXCR4, CD133, EPCAM and SOX9, while others are associated with apoptosis (FASLG, TJP2, DUSP4), the MAPK pathway (MAP2K4, DUSP4), and chemoresistance (MMP1, an ETS1 target gene)." (PMID 24069258, 2013). "MAP2K4 is a putative tumor and metastasis suppressor gene frequently found to be deleted in various cancer types." (PMID 21575258, 2011). "MAP2K7 and MAPK8 may promote disease progression and metastasis, whereas MAPK9 and MAP2K4 may be more protective at certain stages of cancer development." (PMID 41515982, 2025). "In addition, alterations in MAP2K4, FGFR3, and APC genes have been linked to cancer progression and treatment." (PMID 39031010, 2024). "Two of the individual CTCs (CTC1 and CTC2) and the CTC pool had homogenous copy-number profiles, and included amplification on 1q and 8q (MYC), 11q (CCND1, FGF3, FGF4) and allelic loss of regions including several cancer genes on 3p (BAP1), 13q(RB1, BRCA2) and 17p (MAP2K4)." (PMID 36088510, 2022). "The affected genes (MAP2K4 and YTHDF2) have both been implicated in cancer development." (PMID 34158539, 2021). "Cancers that have lost MAP3K1 or MAP2K4 fail to activate JNK-JUN." (PMID 29795445, 2018). "Furthermore, miR-27 acts as an oncogene by targeting the tumour suppressor gene mitogen activated protein kinase 4 (MAP2K4); in turn, MAP2K4 regulates JNK or p38 phosphorylation promoting OS cancer progression." (PMID 29246026, 2017). "Furthermore, in the Rohrbeck Lung (all-Lung, cancer only) dataset Bcl6 expression was positively correlated with MAP2K4, Yes1 and negatively correlated with Dlg2 and Lgl1." (PMID 26187947, 2015). "Importantly, MAP2K4 appears to have a similar pro-invasion/pro-metastatic role in several other cancer types, including breast and pancreatic cancer." (PMID 24339940, 2013). "The genetic evidence for a role of MAP2K4 in cancer is gathering strength." (PMID 21575258, 2011).